SPEN (spen family transcriptional repressor)
Description:
May serve as a nuclear matrix platform that organizes and integrates transcriptional responses. In osteoblasts, supports transcription activation: synergizes with RUNX2 to enhance FGFR2-mediated activation of the osteocalcin FGF-responsive element (OCFRE) (By similarity). Has also been shown to be an essential corepressor protein, which probably regulates different key pathways such as the Notch pathway. Negative regulator of the Notch pathway via its interaction with RBPSUH, which prevents the association between NOTCH1 and RBPSUH, and therefore suppresses the transactivation activity of Notch signaling. Blocks the differentiation of precursor B-cells into marginal zone B-cells. Probably represses transcription via the recruitment of large complexes containing histone deacetylase proteins. May bind both to DNA and RNA.
Synonyms: KIAA0929; MINT; SHARP; RBM15C; HIAA0929; RATARS
Tractability: PROTAC: ubiquitination databases record sites on it; its protein half-life has been measured.
Gene: Protein-coding gene on chromosome 1 (15,836,095 to 15,940,456, forward strand). Ensembl gene ENSG00000065526.
Subcellular location: Nucleus
Subcellular location (Human Protein Atlas): Nucleoplasm
Pathways (Reactome):
Signal Transduction: RHOBTB1 GTPase cycle
Gene Ontology:
Molecular function: protein binding; RNA binding; RNA polymerase II-specific DNA-binding transcription factor binding; transcription corepressor activity; mRNA binding; nucleic acid binding
Biological process: negative regulation of DNA-templated transcription; negative regulation of transcription by RNA polymerase II; positive regulation of neurogenesis; random inactivation of X chromosome; regulatory ncRNA-mediated heterochromatin formation; regulation of transcription by RNA polymerase II
Cellular component: extracellular exosome; nucleoplasm; transcription repressor complex; nucleus
Genetic constraint (gnomAD): Loss-of-function variants: 16 observed, 259.88 expected, observed/expected ratio (o/e) 0.0616, 90% interval 0.041 to 0.094. The upper end of that interval is the gene's LOEUF score, 0.094, which puts it in group 1 of 6, group 1 being the genes least tolerant of losing a copy. Missense variants: 3,766 observed, 4,730.6 expected, observed/expected ratio (o/e) 0.8, 90% interval 0.77 to 0.82. Synonymous variants: 1,702 observed, 1,815.1 expected, observed/expected ratio (o/e) 0.94, 90% interval 0.9 to 0.98.
Gene-disease validity (ClinGen):
ClinGen rates the evidence that SPEN causes each of these diseases.
Radio-Tartaglia syndrome (autosomal dominant): Definitive.
Cancer hallmarks: change of cellular energetics; invasion and metastasis (promotes); escaping programmed cell death (suppresses); proliferative signalling (promotes); suppression of growth (promotes)
Homologues: Orthologues: chimpanzee SPEN (99% identical), macaque SPEN (97% identical), dog SPEN (84% identical), rabbit SPEN (84% identical), guinea pig SPEN (82% identical), mouse Spen (81% identical), rat Spen (80% identical), tropical clawed frog spen (59% identical), zebrafish spen (45% identical), zebrafish SPEN (37% identical), Drosophila melanogaster spen (23% identical). Paralogues in human: RBM15 (7% identical), RBM15B (6% identical), RAVER1 (4% identical), SFPQ (4% identical), RAVER2 (4% identical), PSPC1 (3% identical), NONO (3% identical).
Diseases named in the same sentence as SPEN in open-access papers:
SPEN is named in the same sentence as 62 diseases in open-access papers, as found by Europe PMC text mining. Sharing a sentence is not in itself a finding about the gene and the disease. The quoted sentences say what the papers report.
breast carcinoma (16 papers, 2014 to 2025). "The protein encoded by the SPEN gene acts as an estrogen receptor cofactor and has been shown to have a tumour-suppressor role in regulating tumour growth, cell proliferation and survival in ERα-expressing breast cancer cell lines." (PMID 39010058, 2024). "SPEN is recognized as a tumor-suppressor gene, and its deletion or intragenic mutation may contribute to breast cancer progression." (PMID 38049758, 2023). "Moreover, nonsense mutations in SPEN can also be identified in the ER α-expressing breast cancer cell line T47D." (PMID 29871594, 2018). "In breast cancer cases, it has been suggested that SPEN functions as a regulator for NOTCH and WNT signaling pathways, both crucially involved during tumorigenesis and metastasis processes." (PMID 38392565, 2024). "Recent studies have shown that SPEN is mutated in 5% of splenic marginal zone lymphoma cases, and SPEN functions as a tumor repressor and candidate biomarker of tamoxifen responsiveness in ERα-positive breast cancers." (PMID 38609996, 2024). "Consistently, in gastric cancer and breast cancer, lower endothelial SPEN expression correlated with extended patient survival." (PMID 37607001, 2023). "SPEN family transcriptional repressor (SPEN), also known as the SMART/HDAC1-associated repressor protein (SHARP), has been reported to modulate the malignant phenotypes of breast cancer, colon cancer, and ovarian cancer." (PMID 32641685, 2020). "Specific genes, such as PTEN, protein kinase A (PKA), GSK3B, CREBBP, SPEN have been linked to CSC biology and metastasis in breast cancer." (PMID 33167919, 2020). "CREBBP, NUMA and SPEN have not been linked to breast cancer by the COSMIC CGC but have been statistically determined to be breast cancer drivers by IntOGen." (PMID 39010058, 2024). "Interestingly, similar to SRARP, SPEN is also a transcriptional corepressor of nuclear hormone receptors that has a tumor suppressor function in breast cancer." (PMID 29577611, 2018). "For the non-cancer adipose-breast network that we applied to the breast cancer GWAS, Downstreamer prioritised seven known breast cancer driver genes among the top 100 genes: CREBBP, TRPS1, ARID1A, ARID1B, XBP1, SPEN and NUMA1." (PMID 39010058, 2024).
lymphoma (3 papers, 2023 to 2025). A malignant (clonal) proliferation of B- lymphocytes or T- lymphocytes which involves the lymph nodes, bone marrow and/or extranodal sites. "However, the panel targeted the most relevant genes for lymphoma diagnosis but did not cover all exons for some genes (e.g., KMT2D) and lacked a few select genes (e.g., FAS, SLAMF1, SPEN, and NCOR2), which are described in cutaneous MZL10,32." (PMID 37081015, 2023).
melanoma (3 papers, 2017 to 2024). A malignant, usually aggressive tumor composed of atypical, neoplastic melanocytes. "In our work we have shown that high (>2+) nuclear and cytoplasmic SPEN expression trends to associate with melanomas that have present tumor-infiltrating lymphocytes." (PMID 30662871, 2018). "High (>2+) nuclear plus cytoplasmic expression intensity for SPEN was associated with longer melanoma-specific overall survival (OS) compared to lower (≤ 2+) nuclear intensity (p = 0.048)." (PMID 30662871, 2018). "Less well-known genes in melanoma biology not only may be significantly mutated due to the random effect of ultraviolet radiation, but their mutated status may have potential prognostic significance [e.g., the Spen homolog transcriptional regulator (SPEN)]." (PMID 30662871, 2018). "Protein expression of SPEN by melanoma cells was predominantly nuclear (76%); 23.5% of cores expressed both strong (2+ and 3+) nuclear and cytoplasmic stain (23.5%) and 0.5% of cores expressed predominantly cytoplasmic stain." (PMID 30662871, 2018). "Strong expression staining intensity (2+ and 3+) for SPEN protein, if present in both nuclear and cytoplasmic compartments in melanoma cells, trended to correlate with the presence of tumor-infiltrating lymphocytes (2-way contingency table, χ2 test p = 0.08)." (PMID 30662871, 2018). "SPEN expression was overall higher by melanoma cells compared to stromal cells." (PMID 30662871, 2018). "This association may account for our finding regarding the favorable prognostic significance of patients with high melanoma nuclear and cytoplasmic SPEN expression compared to those with lower (≤ 2+) protein expression." (PMID 30662871, 2018). "Little is known about the role of SPEN, a transcriptional regulator of NOTCH1 and hormone receptor signaling, in melanoma and other cancers." (PMID 30662871, 2018). "Using the semiquantitative 0, 1+, 2+, 3+ scale, 0%, 9.3%, 28.3%, 62.3% of tissue cores exhibited absent, low, intermediate, or strong expression of SPEN by melanoma cells." (PMID 30662871, 2018). "However, SPEN interacts with MSX2, which has been previously highlighted with melanoma." (PMID 39337694, 2024).
ovarian carcinoma (3 papers, 2015 to 2021). A malignant neoplasm originating from the surface ovarian epithelium. "Our splicing regulation network analysis showed some splicing factors might be correlated with prognosis-related AS events, including SPEN, SF3B5, RNPC3, LUC7L3, SRSF11 and PRPF38B, suggesting that these splicing factors could play crucial roles in ovarian cancer development." (PMID 34001978, 2021).
splenic marginal zone lymphoma (3 papers, 2021 to 2024). Splenic marginal zone lymphoma is a rare, indolent B-cell non-Hodgkin lymphoma characterized by abnormal clonal proliferation of mature B-lymphocytes with involvement in the spleen, bone marrow and, frequently, the blood. "In addition, SPEN mutations have also been reported in diffuse large B-cell lymphoma (DLBCL), splenic marginal zone lymphoma (SMZL), and pancreatic carcinoma." (PMID 37620924, 2023).
breast tumor (2 papers, 2020 to 2023).
gastric cancer (2 papers, 2023). A primary or metastatic malignant neoplasm involving the stomach. "Statistical analysis further showed that SPEN expression was significantly upregulated in prostate cancer tissues (p < 0.05), stomach cancer tissues (p < 0.001), and lung cancer tissues (p < 0.001)." (PMID 37620924, 2023).
mantle cell lymphoma (2 papers, 2021 to 2024). Mantle cell lymphoma is a rare form of malignant non-Hodgkin lymphoma affecting B lymphocytes in the lymph nodes in a region called the ``mantle zone''. "Frameshift and non-sense mutations of the SPEN gene have been described in adenoid cystic carcinoma and in mantle cell lymphoma (MCL)." (PMID 33916248, 2021).
nasopharyngeal carcinoma (2 papers, 2020 to 2023). A carcinoma arising from the nasopharyngeal epithelium. "In that study, the authors found that the oncogene SPEN induces miR-4652-3p expression in nasopharyngeal carcinoma (NPC) by activation of the PI3K/AKT/c-JUN signaling and that miR-4652-3p targets and downregulates HIPK2." (PMID 36900356, 2023).
anaplastic astrocytoma (1 paper, 2024).
colorectal cancer (1 paper, 2024). A primary or metastatic malignant neoplasm that affects the colon or rectum. "Our study sheds light on the ramifications of SPEN mutations in colorectal cancer, especially in relation to ICI therapy." (PMID 38392565, 2024).
learning disabilities (1 paper, 2020). "Families with probands with SPEN LGD variants have no family history of DD/ID, learning disabilities, or neurological disease." (PMID 33004838, 2020).
metastatic tumor (1 paper, 2016). "Unique mutations in PCLO and CSMD3 in P3A and P3B, respectively and FLG, MLL3 and SPEN in metastatic tumor M3A are listed in the branches." (PMID 27034009, 2016).
nephronophthisis (1 paper, 2025). Progressive tubulointerstitial injury, inherited in an autosomal recessive pattern, caused by mutations in genes involved in ciliary function, which may result in an end stage renal failure. "In one family, homozygous pathogenic variants in two different genes (SPEN and NPHP4) were identified; to our knowledge, this is the first report of nephronophthisis and Radio-Tartaglia syndrome co- segregating in a family." (PMID 40730687, 2025).
Parkinson disease (1 paper, 2020). A progressive degenerative disorder of the central nervous system characterized by loss of dopamine producing neurons in the substantia nigra and the presence of Lewy bodies in the substantia nigra and locus coeruleus. "Here, we investigated the functions of the RNA-binding protein, SPEN/SHARP, in the context of Parkinson’s disease (PD)." (PMID 33208773, 2020).
psoriasis (1 paper, 2024). An autoimmune condition characterized by red, well-delineated plaques with silvery scales that are usually on the extensor surfaces and scalp. "In particular, we suggest experimental validation of miRNAs hsa-miR-485-3p and hsa-miR-371a-3p and lncRNAs MAP3K14, ERAP1 and SPEN in skin lesions of psoriasis patients treated with biological drugs." (PMID 39337694, 2024). "Finally, little is known about the role of SPEN (Msx2-interacting protein) in psoriasis." (PMID 39337694, 2024).
Radio-Tartaglia syndrome (1 paper, 2025). "In Family C, we identified a previously unreported in-frame deletion in SPEN, which is associated with Radio-Tartaglia syndrome (RATARS)." (PMID 40730687, 2025).
tumor (33 papers, 2016 to 2025). "Splicing of this exitron in SPEN in tumour samples suggests a potential loss of its transcriptional repression function." (PMID 38566894, 2024). "This suggests that SPEN mutations are associated with an inflammatory tumor microenvironment (TME), conducive to ICI therapy." (PMID 38392565, 2024). "Cancer patients with SPEN mutation had distinct tumor immune signatures, higher TMB and MSI and more MMR mutant genes, and further explain an underlying mechanism of the predictive value of SPEN mutation on the immunotherapy efficacy." (PMID 37620924, 2023). "The results showed that, while pRNA ASO slightly promoted tumor growth in the control, it abrogated endothelial SPEN deficiency–induced tumor suppression." (PMID 37607001, 2023). "Tumor growth was retarded in endothelial SPEN–deficient mice compared with that in the control mice." (PMID 37607001, 2023). "Functionally, although both SPEN deficiency and RBPJ deficiency inhibit tumor growth, SPEN deficiency normalizes while RBPJ deficiency disrupts tumor vasculature, and disruption of both leads to normalized tumor vessels." (PMID 37607001, 2023). "Forced pRNA expression or RNPI inhibitors (CX-5461) can mimic the effect of SPEN deficiency in tumor vessels, leading to tumor vessel normalization, which has been shown previously." (PMID 37607001, 2023). "Endothelial SPEN deficiency markedly reduced lung metastasis, consistent with decreased circulating tumor cells." (PMID 37607001, 2023). "Our results suggested that SPEN expression is positively associated with ESTIMATEScore in most cancer types, indicating the high purity of the tumor and better prognosis in cancer." (PMID 37620924, 2023). "The relationship between SPEN and tumour responses and the underlying mechanisms await further investigation." (PMID 36583171, 2022). "JAK1 and SPEN were the top two gene mutations in primary tumors associated with tumor recurrence [OR = 7, 95% CI: 0.71, 69.49]." (PMID 34729947, 2021). "SPEN has recently been implicated as a novel tumour suppressor that regulates cell proliferation and inhibits oestrogen receptor downstream signalling, with a role in resistance to tamoxifen." (PMID 28027312, 2016). "Moreover, pRNA ASO partially but substantially reversed SPEN deficiency–induced tumor vessel normalization, as shown by increased vessel density and decreased pericyte coverage." (PMID 37607001, 2023). "Besides, our results showed that SPEN mutation has distinct tumor immune signatures and correlates with higher TMB and MSI." (PMID 37620924, 2023). "We evaluated tumor vessel phenotype under endothelial SPEN deficiency." (PMID 37607001, 2023). "Tumor cell proliferation and tissue hypoxia were attenuated in endothelial SPEN–deficient mice." (PMID 37607001, 2023). "Then, our data further revealed that those patients with SPEN mutation could predict a better prognosis in pan-cancer and had distinct immune signatures, higher tumor mutation burden (TMB), and microsatellite instability (MSI) in common cancer types." (PMID 37620924, 2023). "Our data have suggested that induction of nucleolar stress by SPEN deficiency–induced pRNA upregulation could normalize tumor vessels and therefore serves as a target for AAT." (PMID 37607001, 2023). "Our analysis also showed better tumour responses for patients with SPEN mutations." (PMID 36583171, 2022).